IL6 (interleukin 6)
Diseases named in the same sentence as IL6 in open-access papers (continued):
Sharing a sentence is not in itself a finding about the gene and the disease.
pneumonia (continued). "Overall, we confirmed that pneumonia in the host was mediated by the Stat3/IL-6 pathway and that blockade of Stat3/IL-6 signaling could significantly attenuate AC infection-induced pneumonia in the host." (PMID 35617354, 2022). "Overall, we are the first to provide direct and systemic laboratory evidence of AC migration route in a nonpermissive host and report that infection with a high dose of AC larvae could result in acute and fatal pneumonia through Stat3/IL-6 signaling in mice." (PMID 35617354, 2022). "In this report, the naïve mock vaccinated group demonstrated at necropsy elevated neutrophil levels in BALF, enhanced microscopic pneumonia and proinflammatory lung cytokine profile, including IL-1β, IL-6 and IL-8, compared to both NA2 VLPs and QWIV group of animals." (PMID 35874791, 2022). "In addition, prominent increases in PCT and IL-6 levels were observed in mild and severe pneumonia cases as compared to those in control cases." (PMID 34643152, 2021). "A study indicated that elevation of IL-6 could be a biomarker for severity assessment or a prognostic indicator in patients with pneumonia, the similar tendency can be discovered in the balance between IL-6 and IL-10." (PMID 34725309, 2021). "Notably, we observed significantly reduced IL-6 concentrations in patients with atypical pathogen pneumonia ARDS compared to ARDS by bacterial pneumonia." (PMID 33673270, 2021). "In addition, there were significant differences in PCT, CRP, and IL-6 levels between severe and mild pneumonia cases." (PMID 34643152, 2021). "DD, FIB, and IL-6 levels in patients with mild 2019-nCoV pneumonia were higher than those in the normal physical examination, and the factors in these patients on the 7th day before being admitted to the hospital were significantly higher than those on the 7th day after they were treated." (PMID 34109187, 2021). "BM-MSCs and UC-MSCs were previously observed to reduce BAL IL-6 in a rat pneumonia model." (PMID 34884645, 2021). "In current research, the inflammatory response stimulated by pathogens such as viruses and bacteria is considered to be the pathogenesis of pneumonia in children, leading to high expression of serum levels of proinflammatory factors such as IL-6, IL-8, and CRP in children." (PMID 34956578, 2021). "Tocilizumab (TCZ), an interleukin-6 (IL-6) receptor humanized monoclonal antibody, is therefore recommended by the Novel Coronavirus Diagnosis and Treatment of Pneumonia guidelines by the National Health Commission of China for severely ill patients with elevated IL-6." (PMID 35004038, 2021). "Therefore, it is an important approach to block the occurrence of cytokine storm and prevent the process of patients with pneumonia by inhibiting the expression of IL-6." (PMID 33746604, 2021). "However, IL-6, IL-1β, and IL-8 expression levels in severe pneumonia patients were increased, and the levels of IL-6 showed the greatest increase." (PMID 33065551, 2020). "Disease severity in hospitalized patients is characterized by severe pneumonia associated with overt inflammatory reaction characterized by high C-reactive protein (CRP) and interleukin-6 (IL-6), low albumin, high sedimentation rate, low eosinophils, and lymphopenia." (PMID 32849908, 2020). "Serum IL-6 and TNF levels are associated with mortality of patients with pneumonia." (PMID 33057343, 2020). "Interleukin-6 (IL-6) is an important cytokine that acts to limit infection-related inflammation; however, its role in co-infected pneumonia remains unclear." (PMID 32038632, 2019). "Together, this paper describes the protective functions of IL-6 during co-infected pneumonia." (PMID 32038632, 2019). "Further dissection of the data into sub-groups of patients who developed pneumonia, meningitis, and other infections (having other infections such as urinary tract infections (UTI) or in addition to pneumonia or meningitis) revealed distinct differences in serum IL-6 levels among these sub-groups." (PMID 29194369, 2017).
pneumonia (continued). "Similarly to C. pneumoniae-induced pneumonia, W. chondrophila-induced pneumonia was associated with the production of pro-inflammatory cytokines such as IL-6 and TNF in the lungs, and IL-6 and IL12p40 in the blood." (PMID 26950066, 2016). "Furthermore, IL-6 serum levels significantly reduced in patients with pneumonia (P = 0.041) and severe pneumonia (P = 0.001) during recovery." (PMID 27905908, 2016). "Using a murine model of pneumonia, we found that siderophore secretion by K. pneumoniae induces the secretion of interleukin-6 (IL-6), CXCL1, and CXCL2, as well as bacterial dissemination to the spleen, compared to siderophore-negative mutants at an equivalent bacterial number." (PMID 27624128, 2016). "This may be attributed to large amounts of inflammatory cytokines, including tumor necrosis factor (TNF)-α, interleukin (IL)-1 and IL-6, which are present during critical pneumonia." (PMID 26928863, 2016). "This meta-analysis suggests that there is no significantly increased risk of pneumonia associated with previously reported IL-6 and IL-10 polymorphisms." (PMID 25708204, 2015). "In a subgroup analysis by pneumonia type, ethnicity, sample size and quality score, no significantly increased risk of pneumonia was found for individuals carrying the IL-6 gene -174C allele." (PMID 25708204, 2015). "IL-1β is associated with severity of infection, IL-6 reflects the severity of stress, and TNF-α may be a marker of pneumonia severity." (PMID 25815231, 2015). "Conversely, the level lung IL-10 were increased starting at 2 hours after initiation of AZM alone or in AMP plus AZM treated mice and sustained up to 6 hr post antibiotic treatment when compared to S. pneumonia infected untreated group (A: IL-6; B: IL-10; C: TNF-α and D: IFN-γ)." (PMID 24565171, 2014). "Pneumonia and MV each increased plasma IL-6, KC and IL-10 levels." (PMID 24731244, 2014). "Systemically, pneumonia caused modest inflammation, with increased plasma levels of IL-6, but not of TNF–α, IL-1β and CINC3 when compared to non-infected controls (p<0.05)." (PMID 23717435, 2013). "IL-6 and CRP levels were significantly associated with pneumonia." (PMID 23935729, 2013). "Age, NIHSS score, IL-6, CRP and dysphagia were significantly associated with pneumonia." (PMID 23935729, 2013). "Overall, the comparison between the experimental and control groups in IL-6 levels was statistically significant [MD = −15.07, 95% CI (−17.31, −12.83), P < 0.00001], supporting the efficacy of Xuanbai Chengqi Decoction as an adjunct in severe pneumonia treatment." (PMID 40342990, 2025). "When lymphopenia co-occurs with elevated IL-6 and CRP, the constellation may represent dysregulated immunity that could both exacerbate tissue injury and increase susceptibility to secondary infections such as pneumonia or urinary tract infection." (PMID 41383227, 2025). "Using PCR-DNA sequence verdicts, the IL-1α (356-bp), IL-1β (423-bp), IL-6 (384-bp), TNFα (490-bp), IL-10 (306-bp), IFN-γ (321-bp), PRDX6 (434-bp), ATG7 (416-bp), NDUFS6 (405-bp), and NOX4 (396-bp) genes were found to have different SNPs in the amplified DNA bases linked to pneumonia." (PMID 40711280, 2025). "An in vivo study of IAV and SARS-CoV-2 coinfection in hamsters showed a significant increase in serum interleukin-6 (IL-6), which is a cytokine that plays a crucial role in the progression of inflammation and could be involved in the observed increased severity of pneumonia." (PMID 38668271, 2024). "Pneumonia may use CRP as a clinical measure instead of TNF-alpha or IL-6." (PMID 39727640, 2024). "Finally, we examined whether the priming effect of IFN-γ on poly(I:C)-induced IL-6 production observed in NCI-H292 cells occurred in vivo using a mouse model of acute pneumonia generated by intratracheal administration of poly(I:C)." (PMID 38030681, 2023).
pneumonia (continued). "The large inflammatory response in SARS-CoV-2-induced pneumonia is due to the overactivation of the immune system, resulting in a "cytokine storm" characterized by the excessive release of inflammatory cytokines, such as interleukin-6 (IL-6) and tumor necrotic factor-alpha (TNF-α)." (PMID 38021879, 2023). "Finally, we demonstrated that the enhanced poly(I:C)-induced IL-6 production by IFN-γ observed in human bronchial epithelial cells could be reproduced in a mouse model of poly(I:C)-induced acute pneumonia." (PMID 38030681, 2023). "Among these pro-inflammatory factors, IL-6 was considered to be a more critical mediator of kidney–lung crosstalk, and IL-6 deficiency protected against AKI-induced lung injury via reductions in the level of IL-8 in lung and serum, thereby diminishing pneumonia and capillary leakage." (PMID 36431113, 2022). "Similarly, an increasing trend of IL‐6 was also detected in children with severe pneumonia." (PMID 35665444, 2022). "Our study reports the migration route of Angiostrongylus cantonensis larvae in non-permissive host mouse and discovers that the larvae could induce fatal pneumonia in mouse lung during acute and early infection phase characterized by activation of Stat3/IL-6 signaling." (PMID 35617354, 2022). "Inhibitors targeting Stat3 or IL-6 could significantly attenuate the pneumonia induced by AC, expanding our understanding of angiostrongyliasis cantonensis and providing effective candidate targets for intervention in AC-induced pneumonia." (PMID 35617354, 2022). "And, IL-6 could be used as an efficient biomarker for the diagnosis of pneumonia." (PMID 35794529, 2022). "Furthermore, we revealed that inhibitors targeting Stat3/IL-6 could notably attenuate severe pneumonia during the early infection phase." (PMID 35617354, 2022). "Similarly, other studies conducted in vitro show that mixing ascorbic acid with monocytes isolated from the peripheral circulation of patients with underlying pneumonia resulted in the diminished production of the proinflammatory cytokines TNF-α and IL-6 and the augmentation of IFN levels." (PMID 36004958, 2022). "Therefore, the increase in serum IL-6 may be involved in the increased severity of pneumonia observed in this study." (PMID 34711897, 2021). "However, little is known about the role of IL-6 in co-infected pneumonia." (PMID 32038632, 2019). "Pneumonia is frequent among aSAH patients developing later on during the course of the disease due to immunosuppression and might be responsible for the surge of IL-6 levels, which may provide resistance against Streptococcus pneumoniae." (PMID 29194369, 2017). "According to the ROC curve analysis, at hospital admission, IL-6 serum levels equal or higher than 21.1 pg/mL and IL-6:IL-10 ratio of at least 9.61 may discriminate severe pneumonia from mild disease with a sensitivity of 76.5%, corresponding to a positive predictive value of 93%." (PMID 27905908, 2016). "The results demonstrated that mechanical ventilation (OR = 4.80), CRP (OR = 1.12), PCT (OR = 1.65), IL-6 (OR = 1.11), and IgA (OR = 0.02) were the independent influencing factors for ACD in children with severe pneumonia." (PMID 41234411, 2025). "During the initial phases of pneumonia, alveolar macrophages release inflammatory cytokines such as tumor necrosis factor-α (TNF-α), IL-10, and IL-6." (PMID 41018059, 2025). "In burn‐ALI mice with secondary pneumonia, CuMPBA restored lung architecture, suppress TNF‐α/IL‐1β/IL‐6 levels, and modulated inflammatory pathways by activating Nrf2 while inhibiting NF‐κB." (PMID 40956292, 2025). "Coinfection led to prolonged viral persistence, enhanced pulmonary immune cell infiltration, and significantly elevated levels of inflammatory cytokines (IL-6, CCL3, CCL4, and G-CSF; p < 0.05–0.001), culminating in severe pneumonia." (PMID 41226526, 2025). "Patients with pneumonia were statistically older and had higher levels of inflammatory markers (CRP, IL-6, and D-dimer)." (PMID 40969806, 2025).
pneumonia (continued). "Salivary biomarkers reflected these trends: salivary IL-10, IL-6, and PCT were all significantly higher in children with pneumonia than in healthy children (all p < 0.001)." (PMID 41018059, 2025). "Our investigation used a PCR-DNA-sequencing procedure to illustrate the difference in immunological (IL-1α, IL1B, IL6, TNF-α, IL10, and IFN-γ) and antioxidant (PRDX6, ATG7, NDUFS6, and NOX4) genes in calves with pneumonia and healthy calves." (PMID 40711280, 2025). "In contrast, some studies showed a lower accuracy of procalcitonin in diagnosing pneumonia, compared to CRP and interleukin 6, and the added benefit of PCT in the NICU was viewed as minimal." (PMID 40257674, 2025). "In an LPS-induced acute pneumonia mouse model, THC significantly inhibited neutrophil migration and reduced neutrophil elastase, TNF-alpha, and IL-6 levels." (PMID 40599866, 2025). "The genes IL-1α, IL1B, IL6, TNF-α, IL10, IFN-γ, and NOX4 had significantly greater gene expression levels in pneumonia-affected calves compared to the CON group." (PMID 40711280, 2025). "The most significant elevation of plasma proinflammatory cytokines (IL-6, IL-1β, MCP-1, IP-10 and TNF-α) at 5 dpi were also detected in Subjects 03 and/or 04, suggesting more severe pneumonia-induced systemic inflammation." (PMID 41157643, 2025). "Together, these subgroup comparisons suggest that while all three markers (IL-6, IL-10, PCT) rise in the presence of pneumonia, only IL-10 and PCT levels (in both serum and saliva) correlated with disease severity, whereas IL-6 did not." (PMID 41018059, 2025). "Children with pneumonia exhibited significantly higher salivary concentrations of PCT, IL-6, and IL-10 compared to healthy controls, with strong correlations observed between salivary and serum levels." (PMID 41018059, 2025). "This study aimed to evaluate the diagnostic and prognostic utility of salivary and serum interleukin (IL)-6, interleukin (IL)-10, and procalcitonin (PCT) in children diagnosed with pneumonia." (PMID 41018059, 2025). "Within the COVID‐19 group, the pneumonia subgroup had lower T‐cell counts but higher levels of inflammatory factors, including C‐reactive protein (CRP) and interleukin‐6 (IL‐6)." (PMID 41146434, 2025). "These were incorporated into a Logistic regression model, which revealed that mechanical ventilation, CRP, PCT, IL-6, and IgA were influencing factors for ACD in children with severe pneumonia." (PMID 41234411, 2025). "In a murine pneumonia model, a high-CBD extract significantly reduced neutrophil migration to the lungs and lowered pro-inflammatory cytokines like IL-1β, MCP-1, IL-6, and TNF-α." (PMID 40599866, 2025). "IL-6 levels were positively correlated with age, C-reactive protein (CRP), and pneumonia severity index (PSI) scores." (PMID 40572766, 2025). "When comparing pneumonia-affected sheep to resistant ewes, the IL-1α, IL1B, IL6, and TNF-α genes were markedly upregulated." (PMID 40711280, 2025). "In preclinical animal models of invasive pneumonia, curcumin modulates pro- and anti-inflammatory factors (COX-2, IL-6, IL-8, and IL-10), induces apoptosis in polymorphonuclear neutrophilic cells, and mitigates ROS damage." (PMID 40918117, 2025). "In our study, we observed a significant increase in IL-6 levels in patients with HIV, and this elevation is even more pronounced in those who have coinfection with pneumonia." (PMID 38251391, 2024). "This makes it a practical option for screening and monitoring pneumonia compared to complex or expensive biomarkers, such as CRP, IL-6, and TNF-a." (PMID 38404841, 2024). "In agreement with previous reports, we confirmed that the proinflammatory cytokines IL-6, TNF-α, and IL-1β accumulated in the lungs of PmCQ2-infected mice, which is a typical response to pneumonia." (PMID 38589976, 2024).
pneumonia (continued). "Similar results were found with a PspA-Ply fusion protein-based vaccine in mice: a significant production of TNF-α and IL-6 in the bronchoalveolar lavage fluid (BALF) was observed, correlating with protection against pneumonia." (PMID 38400196, 2024). "The levels of IL-6 and HNL in pneumonia group were significantly higher than those in non- pneumonia group (all P < 0.05)." (PMID 38233767, 2024). "In the “New Coronavirus Pneumonia Diagnosis and Treatment Program (Trial Version 10),” PCT, CRP, IL-6, and other indicators are regarded as early warning indicators for disease deterioration." (PMID 39533550, 2024). "In vitro analyses revealed substantial reductions in the secretions of tumor necrosis factor-α and interleukin-6 from alveolar macrophages, highlighting the potential efficacy of DXMS-Pal-SLNs in alleviating pneumonia-related inflammation." (PMID 39065575, 2024). "The administration of phages in control non-pneumonia mice indicated the safety of phage treatment and the reduced inflammatory cytokines (TNF-α and IL-6) in the serum of pneumonia mice supported the downregulation of proinflammatory cytokines by phages." (PMID 39012882, 2024). "Ectopic N protein expression in lung tissues led to DNA damage, apoptosis, cytosolic DNA accumulation, upregulation of IFNβ, IL-6, and NKG2D ligands, lung injury, and pneumonia to a greater extent in older mice than in younger mice." (PMID 39138195, 2024). "The findings show that pneumonia patients had considerably greater admission amounts of MMP3, NGAL, and IL-6 than healthy controls." (PMID 39727640, 2024). "This is consistent with previous studies reporting that various cytokines and chemokines, such as IL-6, IL-8, IL-10 and IP10, are elevated in patients with HIV and pneumonia." (PMID 38251391, 2024). "Regarding the mediating pathways between WC and pneumonia, CRP, IL-6, and FEV1 mediated 26.90% (95% CI: 13.98%, 39.83%), 10.23% (95% CI: 2.72%, 17.73%), and 4.67% (95% CI: 0.25%, 9.09%) of the effect of WC on pneumonia, respectively." (PMID 39337223, 2024). "In accordance with this, higher systemic levels of pro-inflammatory cytokines, such as IL-6 and TNF, at discharge can predict both short and long-term mortality after hospitalization for pneumonia." (PMID 36870980, 2023). "IL-6, WBC, L, N, CRP, PCT, PT, DD, BS, AST, ALB, D-Bil, BNP, LDH, and CK-MB differed significantly between moderate and severe pneumonia sets both in training and validation sets (P < 0.05)." (PMID 37950171, 2023). "Multiple pro-inflammatory cytokines have been detected to have a certain amount of expression in the pneumonia model, such as TNF-α, IFN-γ, IL-1β, and IL-6." (PMID 36707501, 2023). "In this study, we analyzed the levels of serum IL‐6, IL‐8, IL‐10, IL‐1β, sIL‐2R and TNF‐α in children with pneumonia." (PMID 37142438, 2023). "Seven hub genes, IL4, IL6, CSF2, IFNG, IL1B, TNF and IL17A, were responsible for Experimental Lung Inflammation, Pneumonitis, Pneumonia and Lobar Pneumonia." (PMID 36989283, 2023). "MRSA-induced pneumonia feces recipients exhibited a trend toward higher bronchoalveolar lavage fluid (BALF) TNF-α, IL-6, IL-1β, CXCl-1, MCP-1 levels, and W/D ratio." (PMID 37823635, 2023). "However, in the progression of pneumonia, cytokine storms caused by excessive responses of M1-type macrophages and the secretion of excessive cytokines such as tumor necrosis factor-alpha (TNF-α), interleukin-1 beta (IL-1β), interleukin-6 (IL-6), and other factors can be fatal." (PMID 37176064, 2023). "In a M. pneumoniae pneumonia mouse model, TFCO significantly reduced the lung damage, suppressed IL-1β, IL-6, and TNF-α production, and curbed TLR2 activation triggered by M. pneumoniae." (PMID 37894556, 2023). "The first wave accounted for 1823 (33%) admissions and exhibited the highest proportion of severe patients: 65% with bilateral pneumonia and 83% with oxygen saturation under 94% during admission and elevated levels of CRP, IL-6, and D-dimer." (PMID 37766248, 2023).